HOTAIR (HOX transcript antisense RNA)
Diseases named in the same sentence as HOTAIR in open-access papers (continued):
Sharing a sentence is not in itself a finding about the gene and the disease.
endometrial cancer (26 papers, 2015 to 2024). Primary or metastatic malignant neoplasm involving the endometrium (mucous membrane that lines the endometrial cavity). "HOTAIR is highly expressed and associated with lymph node metastasis of endometrial carcinoma, and it is used for endometrial carcinoma classification." (PMID 32760226, 2020). "HOTAIR is associated with a variety of human cancers, such as breast, liver and endometrial carcinoma." (PMID 27367027, 2016). "Specifically in endometrial cancer (EC), HOTAIR is found to be up-regulated and may serve as a diagnostic biomarker." (PMID 38981872, 2024). "HOTAIR has been associated with proliferation and invasion in endometrial cancer." (PMID 37171645, 2023). "Our research revealed an overexpression of lncRNA HOTAIR in both endometrial cancer tissues and cell lines, which correlated with a less favorable prognosis in patients with endometrial cancer." (PMID 38981872, 2024). "HOTAIR overexpression in endometrial cancer promotes proliferation by direct inhibition of the tumor suppressor PTEN and activation of the PI3K/Akt pathway." (PMID 35905723, 2022). "Specifically, HOTAIR expression was negatively related to miR-646 in human endometrial cancer tissues." (PMID 34122542, 2021). "SiRNA targeting HOTAIR has been shown to suppress the progression of endometrial carcinoma in vivo, demonstrating that targeting HOTAIR can be a novel therapeutic strategy for endometrial cancer." (PMID 34316694, 2021). "HOTAIR promoted the viability, migration, and invasion of endometrial cancer cells by negatively regulating miR-646." (PMID 34122542, 2021). "Downregulation of HOTAIR inhibits proliferation of endometrial carcinoma at the cellular and tissue levels." (PMID 32760226, 2020). "SiRNA targeting lncRNA HOTAIR has been shown to suppress the progression of endometrial carcinoma in vivo demonstrating that targeting lncRNA HOTAIR can be a novel therapeutic strategy for endometrial cancer." (PMID 31653018, 2019). "Recent studies suggest that overexpression of HOTAIR contributes to the initiation and progression of endometrial cancer." (PMID 28649178, 2017). "In vitro assays confirmed its pro-cancerous functions and proposed HOTAIR as an effective target for treating endometrial cancer, especially for the anti-estrogen therapy." (PMID 28649178, 2017). "The expression level of HOTAIR in endometrial cancer tissues is also higher than in normal endometrial tissues and is correlated with tumor stage, myometrium invasion, and lymph node metastasis." (PMID 27686732, 2016). "Reduction of HOTAIR level in endometrial cancer HEC-1A cells restrained cell proliferation, migration, and invasion." (PMID 27686732, 2016). "E2 seems to constitute an important linkage between expression of these lncRNAs and altered levels of sex hormones as it positively correlates with up-regulation of H19 and HOTAIR in endometrial carcinoma." (PMID 26556343, 2015). "This indicates that HOTAIR may affect the biological characteristics of endometrial cancer by regulating the expression of SOX17." (PMID 38981872, 2024). "LncRNAs that play a role in tumor suppression in endometrial cancer include: FER1L4, GAS5, MEG3, RP11-395G23.3, LA16C −313D11.11, Xist, Linc ROR, MALAT1, HOTAIR, OVAL, SRA, etc., However, the mechanism of cuproptosis-associated LncRNAs in endometrial cancer is still unclear." (PMID 37124623, 2023). "In addition, HOTAIR can regulate the cisplatin-sensitivity of endometrial cancer via the regulation of autophagy by affecting Beclin-1 expression." (PMID 37171645, 2023). "Finally, a recent study showed the participation of the HOX Transcript Antisense RNA (HOTAIR) in the regulation of the resistance to cisplatin in endometrial cancer cells." (PMID 31850214, 2019). "Recently, employing siRNA to target the lncRNA HOTAIR has been suggested to suppress the progression of endometrial carcinoma in vivo showing that targeting lncRNA as HOTAIR can be a novel therapeutic strategy for endometrial cancer." (PMID 29755696, 2018).
endometrial cancer (continued). "Taken together, the overexpression of HOTAIR is a common phenomenon in human endometrial cancer." (PMID 28649178, 2017). "Thus, HOTAIR is not only aberrantly expressed in breast cancer but also in endometrial carcinoma." (PMID 26556343, 2015). "Our study has elucidated a crucial pathway in the pathogenesis of endometrial cancer (EC) involving the interaction between ELAVL1 and HOTAIR, which in turn influences the regulation of SOX17." (PMID 38981872, 2024). "The expressions of HOTAIR are positively related to SOX17, and both are significantly overexpressed in endometrial carcinoma." (PMID 38981872, 2024). "For example, HOTAIR and LSD1 collaboratively repress PRB expression and, thus, reduce progesterone sensitivity in endometrial carcinoma cells." (PMID 34912799, 2021). "Emerging data suggest that HOTAIR, in cooperating with LSD1, suppresses the levels of PR-B expression and confers resistance to progesterone therapy in endometrial cancer cells, while the HOTAIR knockdown leads to increased deposition of H3K4me2 marks onto PR-B chromatin." (PMID 31426393, 2019).
nasopharyngeal carcinoma (25 papers, 2013 to 2024). A carcinoma arising from the nasopharyngeal epithelium. "In human nasopharyngeal carcinoma cells, knockdown of HOTAIR causes a decrease in free fatty acids and FASN at the transcriptional and posttranscriptional levels." (PMID 35036050, 2022). "HOTAIR acts as a sponge and negatively regulates the expression of miR-101, modulating tumor progression of nasopharyngeal carcinoma cells." (PMID 33540611, 2021). "In nasopharyngeal carcinoma patients, HOTAIR expression levels increased with clinical stage progression, and it is associated with poor prognosis." (PMID 34576322, 2021). "Based on an in-situ hybridization assay, 91 of 160 (56.87%) paraffin embedded nasopharyngeal carcinoma (NPC) biopsy specimens had elevated HOTAIR levels." (PMID 32117729, 2020). "HOTAIR is extremely abundant in nasopharyngeal carcinoma cells (NPC) and functions as an angiogenesis activator." (PMID 32549757, 2020). "In nasopharyngeal carcinoma (NPC) HOTAIR is strongly up-regulated in cell lines and tissues, and its knockdown leads to a significant decrease of several angiogenic factors, such as vascular endothelial growth factor A (VEGFA) and angiopoietin 2 (Ang2)." (PMID 31072041, 2019). "Higher expression of HOTAIR was detected in cancer cells than in the corresponding non-tumor cells in various cancers including breast, colon, liver, pancreas and nasopharyngeal cancer." (PMID 24130837, 2013). "Moreover, miR-101 directly binds to the 3’-UTR of COX-2 and downregulates COX-2 expression, suggesting the importance of HOTAIR/miR-101/COX-2 axis in progression of nasopharyngeal carcinoma cells." (PMID 34576322, 2021). "This HOTAIR/miR-101/COX-2 regulatory axis is crucial in nasopharyngeal carcinoma development." (PMID 33540611, 2021). "For example, three circulating lncRNAs (LincRNA-p21, GAS 5, HOTAIR) have been discovered as biomarkers to predict chemoradiotherapy sensitivity in head and neck cancers including nasopharyngeal carcinoma, indicating the important value of circulating lncRNAs in clinical outcome predictions." (PMID 27886062, 2016). "In particular, HOTAIR was found to recruit EZH2 to the CDH1 promoter in nasopharyngeal carcinoma (NPC), leading to its transcriptional repression." (PMID 36509828, 2022). "Recently, HOTAIR was shown to be dysregulated in HNC, including laryngeal squamous-cell carcinoma (LSCC), nasopharyngeal carcinoma (NPC) and oral squamous-cell carcinoma (OSCC)." (PMID 27802187, 2017). "For example, endothelial cells are responsible for supporting tumor neovasculature, also participating in several molecular signaling pathways, and HOTAIR has been identified can regulate VEGF-A and angiopoietin 2 (Ang2) expression in nasopharyngeal carcinoma and glioma." (PMID 32951010, 2020).
lung adenocarcinoma (20 papers, 2013 to 2025). A carcinoma that arises from the lung and is characterized by the presence of malignant glandular epithelial cells. "In NSCLC, elevated expression of HOTAIR is linked to lymph node metastasis and poor survival in patients with lung adenocarcinoma (LAC) and squamous cell carcinoma (LSCC)." (PMID 25491133, 2014). "For example, HOTAIR has been shown to inhibit the expression of the P21 protein, thereby increasing the resistance to cisplatin in lung adenocarcinoma cells." (PMID 40299524, 2025). "Since p21 expression is regulated by PRC2 in lung cancer cells, it is possible that the upregulation of HOTAIR can promote the recruitment of PRC2 to downregulate p21 expression in lung adenocarcinoma cells." (PMID 33291485, 2020). "Mechanistically, HOTAIR increases tumor cell proliferation in lung adenocarcinomas by reducing the expression of p21, an inhibitor of cell cycle progression at the G1 phase." (PMID 33291485, 2020). "It is worth mentioning that over-expression of HOTAIR is positively correlated with resistance to cisplatin in lung adenocarcinoma cell lines." (PMID 30441874, 2018). "The lncRNA HOTAIR (HOX Transcript Antisense RNA) is reported to contribute to cisplatin resistance in human lung adenocarcinoma cells via down-regulating p21WAF1/CIP1 expression." (PMID 30568280, 2018). "For example, the expression of HOTAIR was found to be dramatically upregulated in cisplatin-resistant lung adenocarcinoma cells and expression of HOTAIR by patients’ tumours was negatively correlated with response to cisplatin treatment." (PMID 28430163, 2017). "Overexpression of lncRNA HOTAIR leads to cisplatin resistance in human lung adenocarcinoma cells." (PMID 37035213, 2023). "HOTAIR promotes resistance of lung adenocarcinoma cells to cisplatin via targeting p21 in vivo." (PMID 30441874, 2018). "In a similar study conducted by Liu and colleagues, HOTAIR expression was discovered to be up-regulated in the cisplatin-resistant A549 lung adenocarcinoma cell line model, with consequent re-sensitisation of the cell line to cisplatin exposure following HOTAIR knock-down." (PMID 28273813, 2017). "Moreover, type 1 collagen transcriptionally up-regulates the expression of HOTAIR in lung adenocarcinoma cells." (PMID 25491133, 2014). "HOTAIR to be implicated in cancer metastasis regulation by targeting the chromatin repressor polycomb protein, and linc00673 to activate WNT/β-catenin signaling and aggravate lung adenocarcinoma by binding between casein kinase 1ε (CK1ε) and DEAD box RNA helicase DDX3." (PMID 34630508, 2021). "HOTAIR promotes the DDP resistance in lung adenocarcinoma (LUAD) cells by downregulating p21 protein and overexpressed p21 can rescue the effects of HOTAIR on DDP resistance, which indicates that p21 mediates HOTAIR induced DDP resistance." (PMID 31920650, 2019). "lncRNA HOTAIR promoted cell proliferation and inhibited chemosensitivity to DOX in bladder transitional cell carcinoma, and lncRNA CCAT1 promoted lung adenocarcinoma cell chemoresistance to docetaxel by sponging let-7c." (PMID 28969069, 2017). "HOTAIR promotes proliferation, survival, and resistance to cisplatin through repression of p21WAF1/CIP1 in lung adenocarcinoma cells." (PMID 25491133, 2014).
osteoarthritis (20 papers, 2017 to 2025). A noninflammatory degenerative joint disease occurring chiefly in older persons, characterized by degeneration of the articular cartilage, hypertrophy of bone at the margins and changes in the synovial membrane. "lncRNAs have been found to play a role in NCS; the lncRNA HOTAIR, which has previous associations with osteogenesis and osteoarthritis, was recently found to be dysregulated in NCS and results in impaired osteoclast differentiation." (PMID 38609424, 2024). "Additionally, HOTAIR can drive osteoarthritis progression, which is associated with the regulation of PTEN." (PMID 35027936, 2022). "HOTAIR modulates chondrocyte apoptosis and inflammation in osteoarthritis via the regulation of the miR-1277-5p/SGTB axis." (PMID 35626352, 2022). "Osteopontin-induced HOTAIR expression is involved in osteoarthritis by regulating cell proliferation." (PMID 33446111, 2021). "HOTAIR has been described as a regulator of inflammatory injury, cell apoptosis, and influx of inflammatory cytokines during the progression of osteoarthritis." (PMID 33540611, 2021). "In contrast, it has been shown that HOTAIR is upregulated in osteoarthritis patients and indicates elevated expression of MMPs, as well as chondrocyte apoptosis." (PMID 32791451, 2020). "For example, Huet al. found that HOTAIR promotes osteoarthritis progression through miR-17-5p/FUT2 signaling." (PMID 31481088, 2019). "For example, overexpression of the lncRNA HOTAIR in osteoarthritis cases has been found to promote disease progression." (PMID 30505322, 2018). "LncRNA HOTAIR was highly expressed in osteoarthritis chondrocytes, suggesting that it could be a biomarker for osteoarthritis." (PMID 37779916, 2023). "HOTAIR is downregulated after stimulation with pro-inflammatory cytokines and is expressed at lower levels in knee samples from patients with RA, compared with osteoarthritis." (PMID 38071204, 2023). "Likewise, HOTAIR overexpression plays an important role in osteoarthritis progression, correlating with the modified Rankin scale, extracellular matrix (ECM) degradation, and chondrocytes apoptosis." (PMID 33540611, 2021). "Furthermore, miR‐17‐5p was previously reported to target HOTAIR, thus promoting osteoarthritis progression, and provides a reliable basis for us to study the interaction of HOTAIR/miR‐17‐5p." (PMID 34180119, 2021). "In addition, HOTAIR-NF-κB signaling axis was reported to be involved in aggravating the inflammatory environment of osteoarthritis, releasing epithelial-mesenchymal transition (EMT), and airway remodeling during smoke-induced COPD development, and promoting neuronal injury." (PMID 41567340, 2025). "Therefore, the silencing of lncRNA HOTAIR could result in better prognoses for osteoarthritis patients." (PMID 32791451, 2020). "For example, HOTAIR may promote the death of IL-1β-induced chondrocytes by regulating the miR-222-3p/ADAM10 axis, triggering inflammatory responses, causing extracellular matrix degradation, and inducing oxidative stress during the progression of osteoarthritis." (PMID 41299664, 2025). "It was observed that the expression of HOTAIR was greater in patients with nontraumatic osteonecrosis of the femoral head (ONFH) compared with osteoarthritis samples." (PMID 32714991, 2020). "The expression levels of HOTAIR and miR-17-5p in the mesenchymal stem cells (MSCs) derived from patients with non-traumatic ONFH and osteoarthritis (OA) were examined by real-time PCR." (PMID 28207735, 2017).
gastrointestinal stromal tumor (18 papers, 2013 to 2024). "Overexpression of HOTAIR was also strongly associated with high-grade tumors and metastasis in gastrointestinal stromal tumor specimens." (PMID 32117729, 2020). "Overexpression of HOTAIR is also associated with high-grade tumor and metastasis in gastrointestinal stromal tumors; knockdown of HOTAIR altered the expression of some reported target genes and suppressed cell invasiveness." (PMID 25334066, 2014). "Upregulation of HOTAIR is closely associated with gastrointestinal stromal tumor (GIST) aggressiveness and metastasis and it can be used as a potential biomarker." (PMID 23443164, 2013). "In particular, HOTAIR upregulation has been associated with tumor aggressiveness, metastasis, and poor survival in gastrointestinal stromal tumor (GIST) patients." (PMID 31827510, 2019). "For example, HOTAIR is upregulated and associated with a poorer prognosis in various malignancies, including breast and gastric cancers and gastrointestinal stromal tumor (GIST)." (PMID 39684631, 2024). "In gastrointestinal stromal tumours, the expression of the lncRNA HOTAIR is significantly elevated and this expression is further amplified following imatinib treatment." (PMID 37837401, 2023). "Recently, it was reported that RNA interference-mediated knockdown of HOTAIR altered the expression of HOTAIR target genes and suppressed the invasion of gastrointestinal stromal tumor cells." (PMID 32117729, 2020). "HOTAIR role in metastasis has been confirmed in several cancer types including breast, gastrointestinal stromal tumors, HCC, and non-small cell lung cancer." (PMID 25101115, 2014). "HOX transcript antisense RNA (HOTAIR) is upregulated in a number of different cancers, including breast, colorectal, hepatocellular, and gastrointestinal stromal tumors." (PMID 25400658, 2014). "The knockdown of HOTAIR suppresses the invasiveness of gastrointestinal stromal tumor cells." (PMID 23717443, 2013). "HOTAIR was shown to increase autophagy and promote imatinib sensitivity of gastrointestinal stromal tumors (GIST)." (PMID 36685879, 2022). "The role of HOTAIR in gastrointestinal stromal tumors (GISTs) is remains unclear." (PMID 27659532, 2016).
renal carcinoma (18 papers, 2014 to 2025). A carcinoma arising from the epithelium of the renal parenchyma or the renal pelvis. "In vitro studies have shown that curcumin decreases renal cancer cell migration and invasion by downregulating the expression of HOTAIR." (PMID 40352931, 2025). "Among all the lncRNA candidates predicted by the BiGAN as being associated with renal cancer, 7 lncRNAs were among the top 10 in the predicted list, (MALAT1 1st, HOTAIR 2nd, PVT1 3rd, NBAT1 4th, UCA1 5th, H19 6th, and MEG3 7th)." (PMID 34193046, 2021). "For example, in human renal carcinoma, colorectal adenocarcinoma, and prostate cancer cells, genistein represses HOTAIR by upregulation miR-141." (PMID 33805687, 2021). "HOTAIR expression is negatively correlated with miR-217 in human renal cancer tissues and cells, in this way modulating proliferation and migration, and inhibiting apoptosis." (PMID 33540611, 2021). "In renal carcinoma, HOTAIR can bind with the RBP human antigen R, which then directs HOTAIR to the Let7 miRNA-Ago2 complex and leads to microRNA-mediated suppression of HOTAIR through degradation." (PMID 32117729, 2020). "The overexpression of HOTAIR in renal cancer decreased apoptosis and increased cell migration and invasion." (PMID 31208095, 2019). "HOTAIR is confirmed to promote the malignancy of renal carcinoma cells, and to stimulate oncogenesis by suppressing miR-141 in the RISC complex." (PMID 27556696, 2016). "miR-141 reduces the expression of HOTAIR and a reporter gene that is controlled by the miR-141 target site from HOTAIR in renal carcinoma cells." (PMID 25491133, 2014). "In addition, there is an inverse correlation of HOTAIR with miR-141 expression in renal carcinoma cells." (PMID 37175800, 2023). "In renal cancer cells, HOTAIR is able to interact with miR-141 in a sequence-specific manner." (PMID 33540611, 2021). "Therefore, miR-141, via a sequence-specific manner, can suppress HOTAIR expression in renal carcinoma and colorectal adenocarcinoma cells." (PMID 33805687, 2021). "Oncogene lncRNA HOTAIR is upregulated in numerous tumors and may be involved in curcumin-induced inhibition of renal carcinoma cell metastasis." (PMID 32337261, 2020). "Furthermore, they showed that inhibition of HOTAIR expression resulted in suppression of growth of xenograft tumors formed by renal carcinoma cells." (PMID 25859406, 2015). "Additionally, HOTAIR functions as a ceRNA for miR-217 to induce HIF-1α/AXL signaling, facilitating renal cancer progression both in vitro and in vivo." (PMID 33540611, 2021).